EGFR (epidermal growth factor receptor)
Diseases named in the same sentence as EGFR in open-access papers (continued):
Sharing a sentence is not in itself a finding about the gene and the disease.
infection (continued). "However, our western blotting result showed no significant alteration of the actin from EGFR immunoprecipitates in response to the infection, raising the speculation that this actin protein would be naturally conjugated with EGFR, and this binding might not be attributed to the recruited ACTN4." (PMID 30687645, 2018). "For example, JCPyV infection of human glial cells requires activation of the EGFR and the MAPK pathway, whereas MuPyV also activates EGFR and MAPK but this activation is not required for infection." (PMID 27803182, 2016). "Relative to mock infection, WT and UL138STOP infection decreased EGFR levels by 70–75% (p-value≤0.001), with neither being statistically different from each other." (PMID 27218650, 2016). "In the present study, treatment with L. rhamnosus unexpectedly inhibited EGFR activation, which would not otherwise be adversely affected by F4+ ETEC at 3 h after infection." (PMID 25915861, 2015). "Vein, Keren and rhomboid are transcriptionally induced in the gut upon infection with Ecc15, while spitz but not gurken is expressed in the gut (data not shown), indicating that three of the four ligands could potentially activate the EGFR pathway in the adult gut." (PMID 21176204, 2010). "As expected, on single -positive EGFR−/c-MET+ SK-Mel-23 cells, Ad5/3-DM but not Ad5/3-tE triggered a significant induction of cytokine secretion and activation marker expression compared to Ad5/3-ΔE3 infection." (PMID 41552759, 2026). "Myo6 and EGFR, host factors involved in IAV entry, were detected but not enriched upon infection." (PMID 40623098, 2025). "However, EGFR and p38 inhibitors, but not ERK1/2 inhibitor, significantly improved cell survival of the infected VK2/E6E7 cells at 24 h post infection." (PMID 35720274, 2022). "Since PBMO display distinctly decreased sAREG levels after infection, these cells are not exposed to the antiapoptotic stimulus, resulting in higher cleaved caspase levels compared to CBMO, which are not increasable by EGFR inhibition." (PMID 32082070, 2019). "Compared to the corresponding protein level measured in uninfected cellular extracts, the infection performed with P. gingivalis at a MOI of 100 significantly reduced the expression level of SOCS-3 (5-fold), IRF-1 (5-fold), and EGFR (6-fold), but not STAT-3, in the nuclear extracts." (PMID 28748038, 2017). "To further verify the effect of EGFR and TSP-1 on endothelial function, we first evaluated EGFR and TSP-1 protein levels in partially ligated carotid arteries with or without AAV9-METTL3 OE infection and performed cross sections immunofluorescence staining after 2 weeks." (PMID 35001873, 2022). "Noteworthily, EGFR inhibition did abolish neither infection-induced ERK1/2 nor Akt phosphorylation, suggesting that infection may initiate another signaling pathway which phosphorylates both proteins independently of EGFR." (PMID 32082070, 2019). "There are many consequences of EGFR signaling, not least of which is a Ras/MAPK-driven transcriptional response, which may explain the difference between the in vivo results and the short-term infections in vitro in primary human cells." (PMID 28195529, 2017). "The results showed that infection of HGEC cells with P. gingivalis, but not with heat-killed P. gingivalis, led to significant reductions in expression levels of mRNAs and proteins for SOCS-3, IRF-1, and EGFR, while LPS-Pg over time significantly increased the expression of these mRNAs and proteins." (PMID 28748038, 2017).
lung (78 papers, 2008 to 2025). "Alterations within the EGFR signaling cascade, such as gene mutations, gene amplification, and protein overexpression, have been shown to contribute to colorectal carcinogenesis." (PMID 36050500, 2022). "EGFR mutations have also been found in SCLC; however, SCLC with EGFR mutations is less responsive to TKI therapy than lung AD with EGFR mutations." (PMID 27145273, 2016). "However, exon 20 insertions, which account for 1%-10% of all EGFR mutations, define a distinct subset of lung ADC characterized by a poor response to all currently approved EGFR-TKIs." (PMID 34487971, 2021). "Alternatively, EMT could contribute to the acquired resistance to EGFR inhibitors as implicated in lung cancer." (PMID 30644426, 2019). "Therefore, we consider routine EGFR mutation testing for all Asian lung SQC patients." (PMID 28591695, 2017). "These cells represent an attractive model because they are sensitive to TKIs and harbor EGFRΔGlu746–Ala750, which is the most prevalent EGFR deletion in lung cancer." (PMID 39533106, 2025). "EGFR mutations are found in 19-23% of lung ADC in the United States and up to 64-67% of lung ADC in other regions including South East Asia and Peru." (PMID 34868953, 2021). "This evidence comes from the inability to understand when EGFR is activated and, therefore, represents the driver of colorectal carcinogenesis." (PMID 33233823, 2020). "For example, in EGFR-mutant lung ADC, the median progression-free survival (PFS) after TKI treatment is about 10–13 months." (PMID 31570104, 2019). "Two hundred seventy-six consecutive patients with advanced EGFR-mutant lung ADC treated with first-line EGFR-TKIs were enrolled." (PMID 30352571, 2018). "Although concurrent EGFR-mutation and ALK-rearrangement in lung ADC is more frequent than initially anticipated, we detected no ALK fusion-protein expression, i.e. no sign of ALK-rearrangement, in any of the 23 EGFR-mutated patients." (PMID 29899852, 2018). "KRAS-mutations are one of the most common genetic events in lung ADC and constitutively activate effectors downstream of EGFR, thus they can potentially cause TKI-resistance and be a negative predictive biomarker for response to EGFR-TKIs in NSCLC." (PMID 29899852, 2018). "Thereby, we show for the first time a gradient of EGFR expression whose level increase with the advancement stage of the colorectal carcinogenesis." (PMID 28157706, 2017). "Anit-PD-L1 is a promising treatment option in lung ASC cases in which PD-L1 upregulated and EGFR mutations are present." (PMID 28387300, 2017). "Targeted therapy of EGFR is well established for lung ADC, but frequently fails due to acquired drug resistances." (PMID 27279498, 2016). "Recently, a pooled analysis of two multicenter randomized clinical studies (LUX-Lung 3 and LUX-Lung 6) compared first-line chemotherapy in patients who carried EGFR mutations with afatinib, a second-generation, irreversible EGFR-TKI." (PMID 27001083, 2016). "Accumulation of molecular alterations, including EGFR overexpression and mutations in KRAS and BRAF, contribute to colorectal carcinogenesis." (PMID 23459231, 2013). "Importantly, combination treatments targeting EGFR and YAP/TAZ‐TEAD were effective in restraining lung tumorigenesis by blocking agrin as a central player in this oncogenic module, thereby revealing new vistas to combat EGFR‐driven lung malignancies." (PMID 40165020, 2025). "We report a rare case of a 35-year-old woman presenting bone, hepatic, and lymph node metastatic urothelial carcinoma, harboring a deletion of 24 nucleotides in exon 19 of the EGFR gene with a 5-month response to osimertinib, a third-generation EGFR tyrosine kinase inhibitor." (PMID 40364160, 2025). "As a standard of care, first-line (1L) targeted therapy for advanced EGFR mutation-positive NSCLC, osimertinib, is an effective and tolerable treatment that improves the prognosis of real-world patients with EGFR mutation-positive lung malignancies." (PMID 38785463, 2024).
lung (continued). "In addition to surgery, radiation therapy, and chemotherapy, targeted therapies against the well-characterized oncogenic driver mutations in lung ADC, such as EGFR, BRAF, KRAS, and ALK fusion, have been widely administered as ADC treatments." (PMID 31685806, 2019). "Hence, our observation that EGFR undergoes functional upregulation by Netrin-1 indicates that it may mediate the potentially deleterious effects of Netrin-1 in liver pathologies." (PMID 27031829, 2016). "We performed comparative mRNA expression profiling of 31 ALK-positive, 40 EGFR-positive and 43 ALK/EGFR-negative lung ADC focused on immune gene expression." (PMID 34125345, 2022). "Lung ADC histology represents one of the most important predictors for the testing and treatment of EGFR-mutant patients." (PMID 33906297, 2021). "Bispecific antibodies may also provide an effective treatment for solid tumours non-respondent to available monoclonal antibodies such as the commercial anti-epidermal growth factor receptor (EGFR) antibody cetuximab that shows no efficacy as a monotherapy in BRAF-mutated colorectal cancer." (PMID 33686177, 2021). "We found that MET, EGFR and phosphorylated STAT3 proteins were decreased after LOC389641 knockdown in human lung AD cell lines." (PMID 33318313, 2020). "The study cohort comprised 31 ALK-positive, 40 EGFR-positive and 43 ALK/EGFR-negative lung ADC patients." (PMID 34125345, 2022). "Overall survival (OS) for Stage IV lung ADC at initial diagnosis were analyzed in patients with BRAF V600E or with undetected mutation (no driver mutation/fusion detected in BRAF, EGFR, KRAS, ALK, ROS1, RET, HER2, or MET genes)." (PMID 31234388, 2019). "This occurred in a lung ADC case that showed no alteration at ARMS analysis, an altered pyrogram with the EGFR TKI response (sensitivity) kit but not attributable neither to classical or uncommon mutations affecting EGFR exon 19 so far described." (PMID 23497146, 2013). "Both cleavable JANX008 TRACTr and the non-masked construct induced complete eradication of HCT116 colorectal (CRC) tumors in mice, although the TRACTr exhibited enhanced safety and pharmacokinetic properties relative to the EGFR-TCE in NHP." (PMID 36793863, 2023).
CNS tumors (56 papers, 2014 to 2026). "In additional trials, BrainChild-02 (NCT03638167) delivers EGFR-specific CAR T cells to pediatric CNS tumor patients, and BrainChild-03 (NCT04185038), delivered CD276-specifc CAR T cells to pediatric patients with CNS tumors, including DIPG." (PMID 37152812, 2023). "In contrast, satisfactory results were obtained in CNS tumors, where erlotinib therapy inhibited MB migration in vitro and successfully diminished the levels of phosphorylated EGFR in EPN models." (PMID 36839989, 2023). "Another Phase I clinical trial (NCT 03638167) using EGFR806-specific CAR T cells in children and young adults with recurrent or refractory EGFR-positive CNS tumours is currently recruiting patients." (PMID 36505819, 2022). "Recently, a Phase I study testing locoregional infusion of CAR.EGFR806-CAR T-cells has been opened to enrol paediatric patients with EGFR-positive recurrent/refractory CNS tumors (NCT03638167)." (PMID 34163465, 2021). "To construct a CAR targeting EGFR-expressing CNS tumors, we chose the mAb806 scFv moiety due to its unique binding characteristics." (PMID 31903167, 2019). "Feedback activation of EGFR has specifically been suggested as an escape pathway in BRAFV600E CNS tumor cells." (PMID 28094001, 2017). "Overexpression of EGFR predicts poor outcomes of MBs, small cell GBMs and PNETs, suggesting those three CNS tumor subtypes can be considered as one group for the potential common mechanism." (PMID 24986561, 2014). "While direct RAS mutations are not very frequent, RAS-related signaling pathways are frequently activated in certain CNS tumors such as GBM, through alternative mechanisms like EGFR amplification, NF1 loss, and PDGFR overexpression, which converge on the RAS/RAF/MEK/ERK and PI3K/AKT axes." (PMID 40362343, 2025). "Concerning CNS tumors, published data are available for 10 adult patients treated with CAR-T cells manipulated and redirected against antigens HER2 and EGFR variant III, with encouraging results concerning safety and feasibility, but dismal regarding survival benefits." (PMID 36140466, 2022). "We recommend designing neoadjuvant/adjuvant window of opportunity trials for GBM patients who are positive for mutant EGFR, using next-generation therapeutics targeting EGFR, such as JCN037, an irreversible TKI specifically designed for CNS neoplasms." (PMID 40581663, 2025). "In this real-world study of 187 adult patients, we described the frequency of EGFR Amp, and explored its clinical, radiological and pathological characteristics in diffuse gliomas under the 2021 WHO classification of CNS tumors." (PMID 38595969, 2024). "Similar to integrins, G-coupled receptors, including epidermal growth factor receptor (EGFR), are continuously internalized from the cell surface and display a considerable impact on CNS tumors development." (PMID 35884733, 2022). "Feedback activation of EGFR, represents another mechanistically-distinct resistance mechanism that can provide an escape pathway in BRAFV600E CNS tumor cells." (PMID 28094001, 2017). "In Case 1, it is noteworthy that other hallmark characteristics of GBM, such as EGFR amplification, TERT promoter mutations, or gains of chromosome 7 with loss of chromosome 10, as well as other driver alterations in high-grade CNS neoplasms, were absent." (PMID 40575153, 2025). "Other molecular characteristics of scGBM, including TERT promoter mutations, EGFR amplification, or combined gain of chromosome 7 and loss of chromosome 10 (+7/−10) mentioned in the 2021 WHO Classification of CNS Tumors, were not possible to examine." (PMID 40058218, 2025).
CNS tumors (continued). "Clinical trials testing HER-2-directed CAR T therapy in children with CNS tumors, EGFR-directed CARs for children and AYAs with CNS tumors and B7-H3-specific CAR Ts in patients with DIPG/DMG or refractory pediatric CNS tumors are ongoing (NCT03500991, NCT03638167 and NCT04185038)." (PMID 37781183, 2023). "In addition to the K27M status, other changes, such as the overexpression of EZHIP and alterations in the epidermal growth factor receptor (EGFR), have been reported, which were recently included in the latest 2021 WHO classification of CNS tumors as “H3K27-altered tumors”." (PMID 36140466, 2022).
head and neck tumors (51 papers, 2002 to 2025). "EGFR had been proved to be overexpressed in over 80% of head and neck tumours and the association translates to shorter survival for patients." (PMID 36448260, 2022). "EGFR is overexpressed in over 90% of head and neck tumors, and its expression is associated with a poor prognosis." (PMID 34178665, 2021). "A recent multivariate analysis demonstrated that overexpression of EGFR in subjects with stage II–IV head and neck neoplasms was associated with early relapses, lower disease-free, and overall survival." (PMID 32537431, 2020). "EGFR is overexpressed in head and neck tumours and is associated with radioresistance and poor prognosis." (PMID 29232380, 2017). "EGFR expression has been linked to radio-resistance of head and neck tumors." (PMID 32537431, 2020). "Numerous studies have shown that curcumin and its derivatives have the potential to affect signaling pathways (NF-κB, JAK/STAT, and EGFR) and molecular mechanisms that are crucial for the growth and migration of head and neck tumors." (PMID 39539276, 2024). "The first human Phase 1/2 clinical trial of NIR-PIT using cetuximab-IR700 targeting EGFR in patients with inoperable recurrent head and neck tumours was successfully completed in 2017." (PMID 39498336, 2024). "In clinical practice, several EGFR inhibitors are available to head and neck tumor patients, which are either monoclonal antibodies (cetuximab and panitumumab) or small molecule tyrosine kinase inhibitors (erlotinib, gefitinib, lapatinib, afatinib)." (PMID 39408603, 2024). "Epidermal Growth Factor Receptor (EGFR) protein level is much higher in head and neck tumors than in normal tissues, making it an effective therapeutic target." (PMID 37427120, 2023). "Molecular-targeted therapies using EGFR as the target is widely used in the clinical treatment of head and neck tumors." (PMID 37152052, 2023). "The efficacy of the combination of EGFR-TKIs or monoclonal antibodies with chemotherapies shows remarkable outcomes, including in patients with head and neck tumors." (PMID 36438839, 2022). "The high levels of EGFR expression in head and neck tumors have also been attributed to gene amplification which further result in a high rate of EGFR transcription and induce high mRNA levels." (PMID 33273921, 2020). "The area under the curve for the high expression of EGFR among the malignant head and neck tumors was 0.901 with a specificity of 86.4%." (PMID 33273921, 2020). "High levels of EGFR correlates with metastasis in head and neck tumors as a result of the activating mechanism responsible for proteolytic enzyme-matrix metalloproteinases production." (PMID 33273921, 2020). "Overall, there is paucity of data on the levels of expression of epidermal growth factor (EGFR) in head and neck tumors among the African population, particularly in Ghana." (PMID 33273921, 2020). "Epidermal growth factor receptor can serve as a biomarker in diagnosing and prognosis of head and neck tumors." (PMID 33273921, 2020). "The level of EGFR expression was determined in head and neck tumor and control head and neck tissues with quantitative real-time PCR and immunohistochemistry analysis." (PMID 33273921, 2020). "This study was therefore designed to bridge the gap in knowledge and to provide relevant data on the expression level of EGFR in head and neck tumors in some selected hospitals in Ghana." (PMID 33273921, 2020). "In head neck tumors, EGFR-expression was related to CT invasion, mass effect, size/volume and lower capillary permeability on perfusion CT." (PMID 29732009, 2018). "ADAM17 is a major sheddase responsible for EGFR signaling, which is a widely studied oncogene in head and neck tumors and an potential therapeutic target for OSCC treatment." (PMID 24495306, 2014). "There is increasing evidence that functional crosstalk between GPCRs and EGFR contributes to the progression of colon, lung, breast, ovarian, prostate and head and neck tumors." (PMID 23144692, 2012).